RAD51 (RAD51 recombinase)
Description:
Homologous DNA recombinase that catalyzes strand exchange, a key step in DNA repair through homologous recombination (HR). Binds to single-stranded DNA (ssDNA) in an ATP-dependent manner to form nucleoprotein filaments which are essential for the homology search and strand exchange. Catalyzes the recognition of homology and strand exchange between homologous DNA partners to form a joint molecule between a processed DNA break and the repair template. RAD51 targeting to ssDNA promotes removal of replication protein-A (RPA) from ssDNA and stabilization of RAD51-ssDNA filaments by blocking ATP hydrolysis. Nucleosomal DNA is peeled from the histone surface by the RAD51 filament. Recruited to resolve stalled replication forks during replication stress. Also required for homologous recombination during meiosis by acting as an non-catalytic accessory factor for DMC1 recombinase, enabling proper chromosome pairing and crossing over (By similarity). Plays a role in regulating mitochondrial DNA copy number under conditions of oxidative stress in the presence of RAD51C and XRCC3. Also involved in interstrand cross-link repair.
Synonyms: HsRAD51; hRAD51; RAD51A; RECA; HsT16930; BRCC5; FANCR; MRMV2
Tractability: Small molecule: a structure with a bound ligand is known; a high-quality ligand is known; it belongs to a druggable protein family. PROTAC: UniProt records ubiquitination sites on it; ubiquitination databases record sites on it; a small molecule that binds it is known.
Gene: Protein-coding gene on chromosome 15 (40,694,774 to 40,732,344, forward strand). Ensembl gene ENSG00000051180.
Subcellular location: Chromosome; Nucleus; Cytoplasm; Cytoplasm, perinuclear region; Mitochondrion matrix; Cytoplasm, cytoskeleton, microtubule organizing center, centrosome
Subcellular location (Human Protein Atlas): Nucleoli; Cytosol; Mitochondria
Pathways (Reactome):
DNA Repair: HDR through Homologous Recombination (HRR); HDR through Single Strand Annealing (SSA); Homologous DNA Pairing and Strand Exchange; Presynaptic phase of homologous DNA pairing and strand exchange; Resolution of D-loop Structures through Holliday Junction Intermediates; Resolution of D-loop Structures through Synthesis-Dependent Strand Annealing (SDSA)
Disease: Defective HDR through Homologous Recombination Repair (HRR) due to PALB2 loss of BRCA1 binding function; Defective HDR through Homologous Recombination Repair (HRR) due to PALB2 loss of BRCA2/RAD51/RAD51C binding function; Defective homologous recombination repair (HRR) due to BRCA1 loss of function; Impaired BRCA2 binding to PALB2; Impaired BRCA2 binding to RAD51
Gene expression (Transcription): Transcriptional Regulation by E2F6
Reproduction: Meiotic recombination
Gene Ontology:
Molecular function: ATP binding; ATP hydrolysis activity; chromatin binding; DNA polymerase binding; DNA strand exchange activity; double-stranded DNA binding; enzyme binding; identical protein binding; nucleosome binding; protein binding; single-stranded DNA binding; ATP-dependent activity, acting on DNA; ATP-dependent DNA damage sensor activity; DNA binding; nucleotide binding
Biological process: cellular response to camptothecin; cellular response to ionizing radiation; DNA damage response; DNA recombination; DNA strand invasion; double-strand break repair via homologous recombination; interstrand cross-link repair; regulation of double-strand break repair via homologous recombination; replication fork processing; chromosome organization involved in meiotic cell cycle; DNA recombinase assembly; DNA repair; double-strand break repair involved in meiotic recombination; meiotic cell cycle; mitotic recombination; reciprocal meiotic recombination; regulation of DNA damage checkpoint; telomere maintenance via recombination; telomere maintenance via telomere lengthening; cellular response to cisplatin; cellular response to gamma radiation; DNA metabolic process; meiosis I; mitotic recombination-dependent replication fork processing; response to glucoside; and 3 more
Cellular component: chromatin; chromosome; chromosome, telomeric region; cytoplasm; cytosol; lateral element; mitochondrial matrix; mitochondrion; nuclear chromosome; nuclear ubiquitin ligase complex; nucleolus; nucleus; perinuclear region of cytoplasm; PML body; presynaptic intermediate filament cytoskeleton; protein-containing complex; protein-DNA complex; site of double-strand break; condensed chromosome; condensed nuclear chromosome; nucleoplasm; centrosome
Genetic constraint (gnomAD): Loss-of-function variants: 12 observed, 41.62 expected, observed/expected ratio (o/e) 0.29, 90% interval 0.18 to 0.47. The upper end of that interval is the gene's LOEUF score, 0.47, which puts it in group 2 of 6, group 1 being the genes least tolerant of losing a copy. Missense variants: 231 observed, 440.75 expected, observed/expected ratio (o/e) 0.52, 90% interval 0.47 to 0.58. Synonymous variants: 135 observed, 156.33 expected, observed/expected ratio (o/e) 0.86, 90% interval 0.75 to 1.
Homologues: Orthologues: macaque RAD51 (100% identical), rat Rad51 (99% identical), dog RAD51 (99% identical), guinea pig RAD51 (99% identical), mouse Rad51 (99% identical), pig RAD51 (99% identical), rabbit RAD51 (99% identical), tropical clawed frog rad51 (96% identical), zebrafish rad51 (90% identical), chimpanzee RAD51 (89% identical), Drosophila melanogaster spn-A (66% identical), Caenorhabditis elegans rad-51 (59% identical). Paralogues in human: DMC1 (54% identical), RAD51C (28% identical), RAD51B (24% identical), XRCC3 (23% identical), RAD51D (20% identical), XRCC2 (16% identical).
Diseases named in the same sentence as RAD51 in open-access papers:
RAD51 is named in the same sentence as 266 diseases in open-access papers, as found by Europe PMC text mining. Sharing a sentence is not in itself a finding about the gene and the disease. The quoted sentences say what the papers report.
breast cancer (316 papers, 1999 to 2026). A primary or metastatic malignant neoplasm involving the breast. "Recent observations on in vitro and in vivo preclinical studies on cell cultures and patient-derived xenografts (PDx) indicate that PARP inhibitors are effective in treating prostate and breast cancers, which are characterized by the loss of RAD51 foci." (PMID 41440218, 2025). "RAD51 mutations are rare, and its functional expression in most breast cancers makes it an attractive therapeutic target." (PMID 40764992, 2025). "In preclinical models and patient samples of ovarian and breast cancer, including ascite metastases and in situ carcinomas, reduced DNA damage-induced nuclear RAD51 is positively associated with BRCA1 or BRCA2 gene defects and patient response to PARPi." (PMID 40830526, 2025). "have correlated Rad51 foci to PARPi resistance in BRCA‐mutated breast cancer, others have considered Rad51 upregulation as a marker for PARPi sensitivity beyond BRCA mutation." (PMID 39778077, 2025). "RAD51 is an essential component for fixing radiation-induced DSBs as part of HR, and germline RAD51 mutations are associated with a 10-20 percent lifetime risk in women for ovarian, fallopian tube, or primary peritoneal cancer and a 30% risk for breast cancer." (PMID 40191738, 2024). "Another study found that breast cancer with lymph node metastases was associated with high RAD51 expression." (PMID 37798649, 2023). "Second, these polymorphisms in RAD51 and paralog genes were analyzed and associated with the risk of specific cancer, breast cancer." (PMID 36761956, 2023). "A Japanese study showed that Rad51 gene polymorphisms were found in two patients with bilateral breast cancer." (PMID 36761956, 2023). "In conclusion, this meta-analysis suggests that Rad51 G172T polymorphism is likely associated with an increased risk of breast cancer, significantly in the Arab population." (PMID 36761956, 2023). "Previous meta-analyses evaluated the effect of the Rad51 G135C polymorphism on the risk of breast cancer and other cancers." (PMID 36761956, 2023). "RAD51 is a recombinase that directly interacts with the breast cancer-associated tumor suppressor BRCA2 and this interaction is critical for normal recombination proficiency." (PMID 36243983, 2022). "For example, prodigiosin caused antiproliferation by suppressing RAD51-mediated HR repair in breast cancer cells." (PMID 36012104, 2022). "The overexpression of RAD51 has been found in various cancers, including breast cancer, and it is revealed closely associated with poor survival." (PMID 35096059, 2022). "Overexpression of RAD51 is associated with tumor aggressiveness and is known to confer treatment resistance in a variety of tumors, including breast cancer." (PMID 35409110, 2022). "These suggested that RAD51 gene mutations are associated with a higher risk of ovarian cancers than breast cancers." (PMID 35608067, 2022). "RAD51 mediated HR generally results in error-free repair but requires the breast cancer susceptibility gene BRCA2 which facilitates RAD51 loading onto the resected single stranded DNA." (PMID 36107942, 2022). "For example, breast cancer cells with deficiencies in HR proteins (such as BRCA1) can repair their DNA by either relying on other highly expressed HR-related proteins (such as RAD51 or PARP1) or backup DNA repair pathways such as alt-NHEJ23." (PMID 35610507, 2022). "For example, mutations in BRCA1 and BRCA2 increase the risk of breast cancer, and mutations in RAD51 increase the risk of rectal cancer." (PMID 35991565, 2022). "RAD51, is known to be related to overall poor survival and endocrine resistance in breast cancer and is also linked to regulation of metastasis in TNBC." (PMID 35401937, 2022). "Consistently, the overexpression of RAD51 in breast cancer cells led to increase in DNA breaks and loss of cGAS expression." (PMID 36428789, 2022).
breast cancer (continued). "Ovarian and breast cancer susceptibility (BRCA) genes which have been shown to coordinate with RAD51 to facilitate HR process, are mutated in a small subset (<1–7%) of these cancers thus contributing to genomic instability because of the loss of HR." (PMID 36428789, 2022). "Some cancers, including ovarian and breast cancers, are known to be HR-deficient and often have mutations in the RAD51 paralogs or RAD51 mediators." (PMID 36232958, 2022). "For example, high RAD51 gene expression was associated with aggressiveness, metastasis, and poor survival in breast cancer." (PMID 36139526, 2022). "In breast cancer, high expression of RAD51 has been associated with cancer cell metastasis, tumor chemotherapy resistance, and tumor radiotherapy insensitivity." (PMID 35251986, 2022). "RAD51 was reported to be implicated in various cancers, such as prostate cancer, lung cancer, and breast cancer." (PMID 33952262, 2021). "RAD51-associated protein 1 (RAD51AP1), which induces RAD51 activation, promotes tumor growth and chemoresistance by modulating the self-renewal of breast cancer stem cells." (PMID 34511602, 2021). "Genetic association studies confirm that the RAD51 polymorphisms contribute to the susceptibility of breast cancer in multiple populations." (PMID 34484285, 2021). "Pathogenetic mutations or variants in CHECK2 and RAD51 have been reported to increase the risk of breast cancer." (PMID 34207556, 2021). "RAD51 nuclear foci were detected in treatment naive, FFPE tumor samples, and it was shown that low levels of RAD51 foci in untreated tissue samples associate with clinical response to PARPi of breast cancer patients." (PMID 34702316, 2021). "A low RAD51 score (indicating HR deficiency) was present in 26% of all breast cancer patients and 67% of TNBC patients." (PMID 34959671, 2021). "We also found that the high level of Rad51 was associated with invasive tumorigenesis and poorer prognosis in breast cancer patients." (PMID 33842359, 2021). "They found a significantly increased risk for overall cancers and concluded that RAD51/G135C polymorphism is a candidate for susceptibility to cancer in general, especially for breast cancer." (PMID 33778923, 2021). "High expression of RAD51 in breast cancer was previously shown to increase the risk of brain metastases and micrometastases." (PMID 32190537, 2020). "RAD51C and RAD51D are the most frequently mutated RAD51 paralogs in cancers and are most closely associated with increased ovarian cancer risk, although breast cancer risk is also increased." (PMID 33015624, 2020). "A case-control study on Bangladeshi population was conducted recently where the high risk association between altered gene expression of RAD51 (rs1801320) gene polymorphism and breast cancer development was detected." (PMID 32458654, 2020). "In different ethnicities, RAD51 (rs1801320) and XRCC2 (rs3218536) gene polymorphisms are certified to be a threat aspect of colorectal cancer and RAD51 (rs1801320) gene polymorphism in breast cancer evolution in Bangladeshi population." (PMID 32458654, 2020). "Observed genotype and haplotype frequencies together with respective odds ratios (ORs) and corresponding 95% confidence intervals for Rad51 polymorphisms in breast cancer cases and control subjects." (PMID 31905201, 2020). "In the hereby presented study we examined the role of genetic variability of two proteins belonging to the HR DSB DNA repair pathway—Rad51 and Xrcc3—as a risk factor for breast cancer in Polish population." (PMID 31905201, 2020). "We describe a group of 300 female patients with breast cancer, demonstrating that TT genotype of -4719A/T polymorphism and GG genotype of -4601A/G polymorphism of RAD51 gene was strongly correlated with breast cancer." (PMID 30728902, 2019). "Previous studies suggest that RAD51 gene 135G/C polymorphism was associated with susceptibility to breast cancer and head-and-neck cancer." (PMID 30712190, 2019).
breast cancer (continued). "The deleterious variant R150Q of the human recombinase RAD51 is associated with hereditary breast cancer but predicted by SIFT and PROVEAN to be benign." (PMID 30952844, 2019). "Elevated expression of RAD51 is associated with tumor aggressiveness and is known to confer treatment resistance in a variety of tumors, including ovarian cancer, breast cancer, lung tumors, pancreatic adenocarcinomas, and malignant gliomas." (PMID 31640742, 2019). "We demonstrated a possible correlation of -4719A/T (rs2619679) and -4601A/G (rs5030789) polymorphisms of RAD51 repair gene with breast cancer." (PMID 30728902, 2019). "In confirmation of this study, allele variation in STR marker in RAD51 gene associated with breast cancer." (PMID 30806067, 2019). "In this regard, it is notable that the only confirmed modifier of breast cancer risk, RAD51:c.135G > C, modifies risk only in BRCA2 pathogenic mutation carriers." (PMID 29422015, 2018). "Previous studies demonstrated the requirement of the FA pathway and other HDR proteins, such as Rad51 and the breast cancer susceptibility proteins BRCA1 and BRCA2, for the protection of stalled forks against nascent DNA degradation." (PMID 30422114, 2018). "We demonstrate that cyclin A2 plays a vital role in maintaining adequate levels of MRE11 and RAD51 proteins for proper functioning of HR repair and that its loss sensitizes the breast cancer cells to DNA damaging agents and PARP inhibitors." (PMID 29207607, 2017). "RAD51 G135C is a naturally occurring variant in the 5’ untranslated region of RAD51 that was shown to increase breast cancer incidence in BRCA2 mutation carriers and gastric cancer." (PMID 27513445, 2016). "Another germline variant, RAD51 R150Q, was identified in a study conducted in Japanese hereditary breast cancer patients, yet association with disease incidence was not definitive." (PMID 27513445, 2016). "Here we report on a novel human RAD51 variant found in an aggressive and therapy-refractive breast carcinoma." (PMID 27513445, 2016). "In conclusion, homozygous substitution (CC) at the RAD51 135G > C locus increases the risk of breast cancer significantly." (PMID 26108708, 2015). "We undertook the present study to assess the impact of the RAD51 135G > C polymorphism on breast cancer risk." (PMID 26108708, 2015). "In contrast, two studies targeting human glioblastoma and breast cancer reported the opposite results that high RAD51 expression was associated with better prognostic outcome." (PMID 26046797, 2015). "The group-wise analysis showed a strong association between RAD51 CC genotype and breast cancer risk in Caucasians (I2 = 87.32, Pheterogeneity = 0, OR = 2.139, P = 0.016)." (PMID 26108708, 2015). "We have previously reported that high cytoplasmic expression of RAD51 in breast cancer is associated with significantly increased risk of BM, particularly in combination with high Ki-67 index and ER-negativity." (PMID 25559688, 2015). "Like most of the known breast cancer susceptibility genes, RAD51, XRCC3, and XRCC2 also have a role in DNA double-strand break repair by homologous recombination." (PMID 25918678, 2015). "Literature review suggests that there are contradictory conclusions regarding the association of RAD51 135G > C polymorphism with the risk of breast cancer." (PMID 26108708, 2015). "In the reported study, RAD51 T/T genotype increased the risk of breast cancer in the Polish population." (PMID 25743260, 2015). "In conclusion, the RAD51 135G > C substitution in the homozygous form (CC) increases the risk of breast cancer in an ethnic-specific manner." (PMID 26108708, 2015). "The significance of the RAD51 polymorphism rs1801320 has been best characterized in patients with breast cancer, especially in carriers of BRCA2 gene mutations." (PMID 26339569, 2015). "We found that ethnicity of the study population affected the association of RAD51 135G > C polymorphism with the risk of breast cancer significantly." (PMID 26108708, 2015).